MAGEB6B (MAGE family member B6B)
Synonyms: MAGEB6P1
Gene: Protein-coding gene on chromosome X (26,160,601 to 26,162,410, forward strand). Ensembl gene ENSG00000232030.
Gene Ontology:
Biological process: negative regulation of transcription by RNA polymerase II
Cellular component: nucleus
Homologues: Orthologues: macaque MAGEB6B (89% identical), rat Mageb6l1 (41% identical), rat Mageb4 (38% identical), mouse Mageb1 (37% identical), mouse Mageb2 (37% identical), mouse Mageb3 (37% identical), mouse Mageb6b1 (34% identical), mouse Mageb6b2 (34% identical), mouse Gm5071 (34% identical), rat Mageb6b1 (32% identical), rat Magebl1 (32% identical), zebrafish ndnl2 (18% identical), and 1 more. Paralogues in human: MAGEB6 (80% identical), MAGEB1 (41% identical), MAGEB4 (40% identical), MAGEB2 (38% identical), MAGEB17 (38% identical), MAGEB18 (37% identical), MAGEB3 (36% identical), MAGEB10 (35% identical), MAGEB16 (32% identical), MAGEA10 (32% identical), MAGEA8 (30% identical), MAGEA4 (30% identical), and 25 more.
Diseases named in the same sentence as MAGEB6B in open-access papers:
MAGEB6B is named in the same sentence as 1 disease in open-access papers, as found by Europe PMC text mining. Sharing a sentence is not in itself a finding about the gene and the disease. The quoted sentences say what the papers report.
Obesity (1 paper, 2025). Accumulation of substantial excess body fat. "This analysis identified proteins not previously associated with childhood obesity, to the best of our knowledge, including A2M, PON3, ADAMTSL4, HSPG2 and MAGEB6B, all of which showed decreased levels in children with obesity." (PMID 39972214, 2025).